S100A7 (S100 calcium binding protein A7)
Diseases named in the same sentence as S100A7 in open-access papers (continued):
Sharing a sentence is not in itself a finding about the gene and the disease.
cancer (continued). "Representatives of such proteins include S-100 proteins (S-100A7-psoriasin, A8–calgranulin-A; A9–calgranulin-B); however, they are not highly specific since they have been identified as key players in the pathogenesis of other diseases, such as DM, psoriasis, and various types of cancer." (PMID 36077473, 2022). "However, little is known about how S100A7 induction occurs in cancer cells." (PMID 27203549, 2016). "Therefore, it has been postulated that a better understanding of the regulation on the expression of AMPs such as S100A7 may help to provide alternative resolutions for unmet needs in the treatment of inflammatory skin diseases and cancers." (PMID 26633653, 2015). "Thus, we speculate that with a growing understanding of the role of S100A7 in cell migration, invasion and proliferation pathways, S100A7 may serve as a therapeutic target for the treatment of inflammation and cancer." (PMID 20689826, 2010). "S100 proteins, particularly S100A4, S100A7, and the S100A8/S100A9 heterodimer, are involved in cancer progression, inflammation, and metastasis through their interaction with RAGE." (PMID 39830522, 2024). "To explore the relationship between S100A7 and the TME, we performed a pan-cancer immune checkpoint analysis." (PMID 38499391, 2024). "The 10-biomarker signature in this category additionally incorporating FABP5, C1RL, MMP9, ECM1, S100A7 and CF1, discriminated early-stage cancers from controls with an AUC of 0.92 (0.86–0.97)." (PMID 36807337, 2023). "Many of the genes upregulated, i.e., MMP1, MMP13, S100A7, CEMIP, and CA9 are known to increase in various cancer cells." (PMID 36766731, 2023). "During mammary tumorigenesis S100A7 increases the expression of reactive oxygen species (ROS) and VEGF by RAGE-dependent mechanisms, thus enhancing cancer cell progression by promoting oxidative stress responses and angiogenesis." (PMID 35727208, 2022). "S100A7-mediated RAGE activation is crucial in modulating pro-inflammatory and angiogenic pathways in many cancer types, particularly in cervical, breast, and esophageal squamous cell carcinoma." (PMID 35727208, 2022). "By facilitating the communications between BC cells and adjacent endothelial cells, S100A7 may be included among the soluble mediators of the microenvironmental secretome, which has gained enormous research interest for providing a valid platform in novel anti-cancer strategies." (PMID 33557316, 2021). "To further investigate the effect of S100A7 on ESCC metastasis, we performed Transwell assays to characterize cancer cell migration and invasion abilities in vitro." (PMID 34323409, 2021). "But we found S100A7, CHCHD2 and SQSTM1 directly interacted with Akt that plays a vital role in signalling pathway of cancer cells." (PMID 24991204, 2014). "The expression of PIGR, DEFB1, LTF, CLU, SCGB2A1 and S100A7, while having a positive role in cancer elimination, were either downregulated or not changed in all or some of the BC subtypes." (PMID 38589404, 2024). "Therefore, we first analyzed the expression patterns of these proteins in the TCGA‐BLCA and Xiangya BLCA cohorts and found that S100A5, S100A7, S100A11, S100A14‐16, and S100B were significantly higher in carcinoma tissues than normal tissues in both cohorts." (PMID 37414584, 2023). "High S100A7 expression also markedly correlated with poor disease-free survival (DFS) in patients with UCS but not in other cancers." (PMID 35205150, 2022). "S100A7 could bind with RAGE receptor on the HUVEC outer membrane, which suggested that S100A7 secreted by cancer cells might promote angiogenesis by activating the RAGE pathway." (PMID 34323409, 2021). "S100A7 activated migratory and invasive abilities through the EMT signaling in cancer cells." (PMID 31731716, 2019).
cancer (continued). "S100A7 is one of the most highly expressed genes in cancer tissues compared to normal breast tissue, where its expression is almost undetectable according to the serial analysis of gene expression (SAGE) database of the Cancer Genome Anatomy Project." (PMID 31731716, 2019). "Of the 72 skin SCC specimens we evaluated, 90.2% (65/72) were well or moderately differentiated carcinomas and the sixty-four specimens were positive for S100A7 expression, whereas none of the six poorly differentiated carcinomas expressed S100A7." (PMID 27203549, 2016). "The slight difference in the inhibitory effect of S100A7 siRNA indicated that cellular phenotypes of carcinoma cells could be partially affected by the nonspecific toxicity with a combination of cell culture conditions as previously reported." (PMID 28629450, 2017). "Although for most S100s, and for HMGB1, the transcript levels were lower in the control HPNE cells than in the cancer cell lines, this was not the case for S100A4, S100A6, S100A7, S100A12, and S100A13." (PMID 37627239, 2023).
infection (26 papers, 2009 to 2026). The state of being infected such as from the introduction of a foreign agent such as serum, vaccine, antigenic substance or organism. "The knockdown efficiency was verified by RT‐qPCR, and the mRNA expression of S100A7 was reduced in OLP lesion tissues after sh‐S100A7 infection." (PMID 40560736, 2025). "In the non-infection model, the S100A7 mRNA expression was significantly elevated with increasing IFN-λ1 concentration." (PMID 33828484, 2021). "After infection, hBD1, hBD3 and S100A7 mRNA expression in IFN-λ1 10 ng/ml group were significantly increased." (PMID 33828484, 2021). "Decreased expression levels of β-defensin 3, LL-37, Elafin, and S100A7 at 6 h post-infection and IFNs at 24 h post-infection have also been observed." (PMID 32850501, 2020). "Taken as a whole, our results underline the major role of the flagellum in the induction of S100A7 expression and production during epidermis infection with P. aeruginosa for E. coli." (PMID 30070169, 2018). "In contrast, during RHE infection with ∆fliC or triple mutant strains, S100A7 protein tissue expression was comparable to the basal level observed in a negative control." (PMID 30070169, 2018). "Alternatively, or in concert, S100A7 expression may reduce the likelihood of secondary infection after fungal disruption of the skin barrier given its antibacterial properties." (PMID 40599378, 2025). "While it is not currently known whether ZnuD shares the S100A7 binding ability of TdfJ, these results suggest that interaction with S100A7 may play a critical role in establishing infection." (PMID 31998268, 2019). "This interaction, limited to the human host, may provide a clear selective advantage to N. gonorrhoeae in the context of infection, especially at the mucosal epithelium, a biologically relevant niche for the gonococcus where S100A7 is enriched." (PMID 31369630, 2019). "We report a strong induction of numerous pro-inflammatory cytokines, chemokines and AMPs such as CXCL1, CXCL2, CXCL5, CXCL8, CCL20, TNFα, TSLP, IL-23α, IL-32, IL-6, hBD2 and S100A7 during the infection of monolayered primary keratinocytes and reconstructed epidermis with the wild-type PAK strain." (PMID 30070169, 2018). "Moreover, we have previously detected S100A7 in tonsillar epithelium and lymphocytes (CD19+, CD4+ and CD8+ cells) and found reduced levels in tonsils in response to infection and atopic predisposition." (PMID 22230654, 2012). "However, it is noteworthy that such strength of interaction may not be entirely necessary, as gonococci seem likely to encounter an abundance of calprotectin and S100A7 during infection." (PMID 35862777, 2022). "The cytokine IL-17A has the function of inducing granulopoiesis, inflammatory response, recruiting neutrophils, inducing fungicidal activity, inducing microbial peptides such as S100A7, S100A8, and promotion of resistance to infection." (PMID 33302372, 2020). "At a later time of infection (16 h), reduced expression of IL-23α, TSLP, hBD2 and S100A7 was observed following keratinocyte infection with T3SS mutant strain compared to wild-type strain." (PMID 30070169, 2018). "S100A7, elafin, and sPLA2 showed a similar profile; their production by the AMN compartment was significantly induced at 24 h post-infection in comparison to the controls, while the bacterial challenge did not modify these peptides synthesis in the CHD compartment." (PMID 35328414, 2022). "Notably, the upregulated genes included S100A7, THBS1, Myosin, and TUBA, which were involved in the immune and infection response." (PMID 35311085, 2022). "However, CP is not the only zinc binding protein found at sites of infection, with humans producing both S100A7, secreted by keratinocytes, and S100A12, secreted by neutrophils, as well as other unidentified mechanisms for restricting zinc availability." (PMID 40463161, 2025).
adenocarcinoma (6 papers, 2015 to 2025). A common cancer characterized by the presence of malignant glandular cells. "On the other hand, the S100A7 protein was only expressed in a few adenocarcinoma cells." (PMID 26544866, 2015). "Indeed, the SCC marker DNp63 was significantly downregulated, and the adenocarcinoma markers TTF1 and napsin A were markedly upregulated, suggesting that silencing of S100A7 attenuated lung ADC to SCC transdifferentiation." (PMID 28177901, 2017).
bacterial infection (4 papers, 2019 to 2025). "Coupled with the increase in S100A7, IL36G, and PI3, which are associated with bacterial response, these data indicate a compromised epidermal barrier and bacterial infection in high bleeders." (PMID 41156831, 2025). "This was particularly surprising in light of the wide use of transgenic mouse models to investigate human S100A7 function, particularly as models for bacterial infections in humans." (PMID 37769710, 2023). "For bacterial infections, if indeed mS100A7 is not actually an S100A7, then the question remains as to what is the primary epithelial S100 protein in mouse?" (PMID 37769710, 2023).
inflammation (2 papers, 2021 to 2025). Aberrant reaction of the microcirculation characterized by movement of fluid and leukocytes from the blood into extravascular tissues. "Consistent with previous mouse studies, genes associated with epidermal inflammation (e.g., IL-6, IL1B, S100A7, S100A8, and S100A9) and matrix metalloproteases (MMPs) were also significantly upregulated, as were E- and L-selectin, which are required for leukocyte entry into skin." (PMID 41150413, 2025).
S100A7 also shares sentences with these, for which no sentence is quoted: adenocarcinomas of the stomach (2 papers); Darier disease (2); esophageal carcinoma (2); hyperplasia (2); larynx (2); mycosis fungoides (2); rheumatoid arthritis (2); skin cancer (2); adenous (1); adult T-cell leukemia (1); alcohol abuse (1); Allergy (1); amyloid (1); anal carcinoma (1); atherosclerosis (1); autoimmune pancreatitis (1); bilirubin encephalopathy (1); cervical intraepithelial neoplasm (1); colon adenocarcinoma (1); contact dermatitis (1); Crohn disease (1); cutaneous squamous cell carcinoma (1); epithelial dysplasia (1); fibrosis (1); glioblastoma multiforme (1); glioma (1); hidradenitis suppurativa (1); intestinal inflammation (1); intrahepatic cholangiocarcinoma (1); lichen sclerosus et atrophicus (1).
A further 18 diseases each share a sentence with S100A7 in 1 paper.